CD44 (CD44 molecule (IN blood group))
Diseases named in the same sentence as CD44 in open-access papers (continued):
Sharing a sentence is not in itself a finding about the gene and the disease.
tumor (continued). "It is found that CD44‐positive CAFs are detected in both vascularized and non‐vascularized areas of tumours and seem to connect with CD31‐positive endothelial cells." (PMID 28523716, 2017). "We found that compared with free drugs and uncoated NPs, particularly given the interaction between HA and CD44, HA-coated NPs enhanced drug accumulation by effectively transporting NPs into CD44-overexpressed tumor cells and inducing cell apoptosis." (PMID 28068992, 2017). "Relatively higher expressions of TGF-β1, CTGF, p-Smad3, p-ERK1/2 and CD44 protein were observed in xenograft tumor treated with TMZ." (PMID 28617438, 2017). "CD44 expression has been shown to contribute to the characteristics of BCSCs such as tumor metastasis and drug resistance." (PMID 28054666, 2017). "As CD44 expression has been proved in most malignancies, the exact role of this molecule in carcinogenesis and tumour biology is still unclear." (PMID 28659655, 2017). "We also found that the endpoint tumours derived from miR-141-overexpressing PCa cells expressed lower levels of CD44 mRNA and protein than the control tumours." (PMID 28112170, 2017). "0.0001) in CD44+/CD90− cells (anticipated epithelial tumor cells) compared with medium derived from other CD44+/CD90− cultivated separately." (PMID 29029509, 2017). "Thus, CD44 and its variant isoforms might be associated with tumor-promoting processes." (PMID 29062810, 2017). "The facts above raise a possibility that CD44 plays a critical role in glucose metabolism via regulation of downstream metabolic genes, which probably is involved in tumor proliferation, invasion and migration." (PMID 29029419, 2017). "By first confirming the under-expression of miR-141 in PCa stem/progenitor populations, here we show that miR-141 is most highly under-expressed (compared with the other three miRNAs) in patient tumour-derived CD44+ HPCa cells." (PMID 28112170, 2017). "The nanoparticles around 20 nm were delivered into the tumor to actively target and be internalized in CD44+ CSLCs by EPR effect." (PMID 28261093, 2017). "This is in line with previous studies that demonstrated an increase of CD44 expression in cells derived from metastatic lesions compared to primary tumor cells." (PMID 29371972, 2017). "Several markers have been defined to isolate GICs from the bulk of the tumor: CD133, encoded by PROM1, CD44, L1CAM or ITGA6." (PMID 29088733, 2017). "Recent studies have shown that CD44 is also detected in tumor stem cells which have the unique ability to initiate tumor cell-specific properties." (PMID 28837080, 2017). "CD44+ cells were able to form a tumor even at a cell concentration of 100 times lower (104 cells/ mouse) if compared with the introduction of a total EC population (106 cells / mouse)." (PMID 28622715, 2017). "The mRNA levels of c-myc, Birc5, Cd44, Lgr5, Tcf7, Mmp7, and Ephb3 were significantly increased in tumor area compared with non-tumor area." (PMID 28710436, 2017). "FNAB tumor sample show slight changes both in the concentrations and where both EpCAM and CD44 are located throughout the tumor after 12 and 24-hour perfusions." (PMID 28085924, 2017). "In contrast, CD44 contributed to tumor formation and progression predictive of poor clinical outcome." (PMID 28659634, 2017). "In support of the evidence in primary tumor cells, where CD44hiCD133lo cells exhibited the progenitor cell markers, the CD133lo cells showed similar marker profile except for CD44 expression." (PMID 29162051, 2017). "The percentage of CD44+/CD24− cancer stem cell in bulk tumor of group 1 group is increased from a mean of 4.7% at baseline to 13.6% (p < 0.001) after 12 weeks of chemotherapy." (PMID 28445439, 2017). "HNSCC contains a small subpopulation of cells that exhibit a hallmark of CD44-expressing cancer stem cell (CSC) properties with self-renewal, multipotency, and a unique potential for tumor initiation." (PMID 28837080, 2017).
tumor (continued). "CEA.Tg mice bearing MC32A tumors and treated with the vaccine alone had significantly higher (*P ≤ 0.05) percentages of Ki67+/CD44+ CD4+FoxP3- T cells in the tumor microenvironment." (PMID 29088720, 2017). "miR-141 re-expression inhibits clonal and clonogenic properties in CD44+ and bulk PCa/HPCa cells in vitro, as well as tumour regeneration in four xenograft models." (PMID 28112170, 2017). "CD44 is a broadly distributed cell surface glycoprotein found on hematopoietic cells, fibroblasts, and numerous tumor cells and has seven extracellular domains, a transmembrane domain, and a cytoplasmic domain." (PMID 29077041, 2017). "We observed an increase in CD44 expression in tumor cells MCF-7 and IBH-7 incubated with hATT-CMs compared to the value observed with hATN- or control-CMs." (PMID 28173833, 2017). "Al-Hendy’s group suggested that Stro-1/CD44+ progenitor cells in the myometrium are the likely tumor initiating cells." (PMID 28438190, 2017). "Several studies reported that the specific activation of apoptosis in tumor cells depends on the interaction of oligo-HA with CD44." (PMID 29062810, 2017). "The first line of evidence for the existence of BCSCs demonstrated that a celluar population with CD44+CD24- phenotype displayed the capacity to initiate new tumours in NOD/SCID Mice." (PMID 29221160, 2017). "The CD44+ cells maintained heterogeneity of the primary tumor after sequential transplantation, thereby complying with the functional standard for stem cells." (PMID 29029546, 2017). "It was wide accepted CD44 was a multifunctional cell membrane receptor involved in cell adhesion, tumor invasion and metastasis." (PMID 29029419, 2017). "Following exposure of tumor spheres to radiations an increase of stem-like CD271+/CD44+ cells was observed." (PMID 28930282, 2017). "They found that a small fraction of cells exhibiting CD44+/CD24−/Lineage (Lin)− phenotype on surface had higher tumor-forming ability in immunocompromised mice and self-renewal property in reiterated passage than CD44+/CD24+/Lin− cells." (PMID 28445439, 2017). "Since CD44s and CD44v6 fail to distinguish normal from benign or malignant epithelia, these two CD44 isoforms cannot be used as reliable tumor markers for monitoring HNSCC progression." (PMID 28837080, 2017). "Very interestingly, HA is the specific ligand for CD44, which are highly expressed in many tumor cells, including CRC." (PMID 28994324, 2017). "The majority of tumor cells derived from metastatic sites of BC patients were highly enriched for a CD44+/CD24− subpopulation." (PMID 28445439, 2017). "Overall, we observed that tumor-derived cell lines that had a high content of CD44+/CD24− cells were more sensitive to the inactivation of these genes." (PMID 28092266, 2017). "Enforced expression of miR-141 in CD44+ and bulk PCa cells inhibits cancer stem cell properties including holoclone and sphere formation, as well as invasion, and suppresses tumour regeneration and metastasis." (PMID 28112170, 2017). "Overexpression of CD44 contributes to key cancer processes including tumor invasion, metastasis, recurrence, and chemoresistance." (PMID 28212584, 2017). "Four out of five control tumours were CD44+/CD24+ whereas all Six1-downregulated tumours lost that phenotype and were CD44−/CD24+." (PMID 28388884, 2017). "An in vivo serial transplantation assay was performed using CD24, CD44 and EpCAM-selected cells from xeno-B110 to determine if they were able to self-renew by initiating new tumours up to the fourth generation." (PMID 28959019, 2017). "The evidence of cancer stem cells as a part of Ehrlich carcinoma and significance of CD44+ and CD44– subpopulations in maintaining the growth of this type of tumor were demonstrated." (PMID 28622715, 2017).
tumor (continued). "HA has been shown to influence cell behavior during embryonic development and tumor development by interacting with cell-surface receptors such as the type I transmembrane protein CD44 and hyaluronan-mediated motility receptor (HMMR)." (PMID 28207787, 2017). "Knowing the role of CD44 in tumor cell migration, we validated this function in GBM tumor cells and stem cells." (PMID 28279210, 2017). "According to our results, factors released by mesenchymal type of cells, which do not express CD44 (CD44−/CD90+), are able to support a growth of CD44+/CD90− type of cells (epithelial tumor cells)." (PMID 29029509, 2017). "Once Sam68 is activated by GTPase RAS, some invariants (including CD44 of Exon V5) will be produced to promote tumor progression." (PMID 28881705, 2017). "Through a paracrine loop, Shh also promotes the proliferation of epithelial cells, including CD44 positive tumor stem cells." (PMID 29166909, 2017). "In summary, our data demonstrated that HPßCD-HET0016 decreases MMP-2 and -9, CD44, and N-cadherin expression, migration and invasion of tumor cells and consequently reduces lung metastasis." (PMID 28609459, 2017). "In this respect, the expression of a sialofucosylated glycoform of CD44 termed HCELL for hematopoietic cell E/L-selectin ligand on tumor cells is of great interest." (PMID 27683128, 2017). "The CD44+ cell fraction showed a highly consistent copy number profile with both, the primary tumor and the unsorted pleura sample." (PMID 28423035, 2017). "Previous studies from our group and others have shown that ALDH+, CD44+/CD24low/- cells have the ability to form a tumor in mice with serial dilution experiments." (PMID 28817737, 2017). "Initiations of EC by introducing of CD44+ cells at concentrations of 3 × 106 and 3 × 105 cells per animal resulted in almost 100% tumor development for both cases." (PMID 28622715, 2017). "Previously, cellular subpopulations from tumor tissue such as CD54+CD44+18, CD26+27, CD133+CD44+28, and CD133+CXCR4+29 had been sorted and identified as CICs or MICs." (PMID 29105339, 2017). "According to the data, the highly malignant and poorly differentiated tumor cells through maintenance of stemness state were ascribed to nuclear CD44 in liver cancer stem cells." (PMID 28819584, 2017). "Remarkably, this CTC-subset displayed tumor stem-like features, as evidenced by the expression of key stem-like genes including Bmi1, CD44, Oct4, Notch1, Wnt3a, Stat3, and HIF-1α." (PMID 27738343, 2017). "CD44 can be cleaved at the membrane-proximal region of the ectodomain by MT1-MMP (membrane type 1 matrix metalloproteinase), which is thought to play an essential role in CD44-mediated tumor cell migration alongside with extracellular matrix components." (PMID 28403901, 2017). "In trastuzumab-treated HTM, CD44 expression was triggered in leucocytes located in the spleen but it was only rarely visible in the tumor tissue or in other organs (e.g. liver)." (PMID 27835865, 2017). "We found an increased migratory potential and enhanced tumor invasion of metastatic OS cells expressing high levels of CD44." (PMID 29371972, 2017). "The liposomal-CDF was determined to inhibit proliferation, tumor formation and CD44 expression in the cisplatin-resistant CCL-23R and UM-SCC-1R HNSCC lines." (PMID 28611316, 2017). "The expression of CD44 isoforms can be correlated with tumor subtypes and be a marker of cancer stem cells." (PMID 28326306, 2017). "Knockdown of CD44 suppresses colony formation and dramatically reduces tumor formation in xenografts." (PMID 29064439, 2017).
tumor (continued). "The intensities of CD31 and CD44 immunostaining were significantly (P<0.02 and P<0.001) decreased in tumor tissue compared with vehicle control." (PMID 28404939, 2017). "One of the established tumor biomarkers is the cluster of differentiation 44 (CD44), an adhesion/homing molecule and the major receptor for HA." (PMID 28403901, 2017). "Medium derived form CD44−/CD90+ caused significant downregulation in expression of IL6 (p=0.0001) in CD44+/CD90− cells (anticipated epithelial tumor cells) compared with medium derived from CD44+/CD90−." (PMID 29029509, 2017). "CD44 functions in carcinogenesis through binding to extracellular matrix components and messenger molecules in tumor environment." (PMID 28659634, 2017). "Multiple studies have demonstrated the involvement of tumor promoting ECM-integrin α5β1 interactions, tumor enhancing hyaluronan-CD44 interactions, and CAF-mediated TGFβ secretion in tumor progression." (PMID 28841710, 2017). "As a compelling stem cell marker, CD44 has been reported to play important roles in tumor initiation and metastasis." (PMID 28030817, 2017). "This supposition about the dependence of EC on functional activity of a subpopulation of CD44+ cells was tested when evaluating the intensity of tumor growth induced by CD44+ and CD44– factions and EC total population." (PMID 28622715, 2017). "It is a negative regulator of nuclear factor-kappa B (NF-kB) and MAPK signaling pathways in CD44-positive tumor cells, and a positive regulator of Sarcoma (Src) and STAT3." (PMID 28445439, 2017). "Of clinical relevance, lentiviral-mediated miR-141 overexpression inhibited clonal growth and serial sphere formation in CD44+ and bulk HPCa cells from patient tumours." (PMID 28112170, 2017). "Hyaluronic acid, specifically bind to the CD44, is a promising ligand for tumor targeting due to overexpression of CD44 on various tumors including the colon, pancreas, breast, and ovarian." (PMID 29552041, 2017). "Based on enhanced gene copy number as well as gene expression detected by aCGH and gene expression analyses, respectively, we decided to evaluate the role of CD44 overexpression in tumor cell behavior and resistance to standard chemotherapy in vitro." (PMID 29371972, 2017). "FASN-induced tumor progression is mediated by CD44, a transmembrane protein that promotes tumor invasion via activation of Akt signaling pathway." (PMID 29100311, 2017). "In CD117+CD44+ CSCs, tumor growth and metastasis were significantly inhibited by downregulation HOTAIR expression." (PMID 29110645, 2017). "Our experiments demonstrated that SH down-regulated CD44 and Sox-2 expression in primary tumor specimens and metastatic lung specimens." (PMID 28088791, 2017). "Our new findings suggested that HA-coated chitosan NPs enhanced drug accumulation by effectively transporting NPs into CD44-overexpressed tumor cells, and they also resulted in mitochondrial damage induced by the production of reactive oxygen species (ROS)." (PMID 28068992, 2017). "Allele frequencies of somatic single nucleotide variants were analyzed in order to further determine if EPCAM+CD44+CD49f+ cells isolated from the lymph nodes were analogous to EPCAM+CD44+CD49f+ cells isolated from the primary tumor." (PMID 28487492, 2017). "Recently, several studies indicate that overexpression of both CD44 variant isoform (CD44v3) and ALDH1 correlates well with tumor formation and HNSCC progression." (PMID 28837080, 2017). "Our results indicated that CD44+ CSC lineage-specific induction of tumour malignancies was controlled by Musashi-1." (PMID 28526879, 2017). "We next constructed a nomogram including histological grade, tumor grade and CD44/CD133/SOX2 expression levels." (PMID 28262804, 2017). "The cell adhesion molecule, CD44, is a trans-membrane glycoprotein that binds hyaluronic acid, facilitates tumor invasion, and promote tumor recurrence." (PMID 28507278, 2017).
tumor (continued). "Of note, CD44 was found overexpressed in drug-resistant OC cell lines and up-regulated in mouse models of tumor recurrence following chemotherapy." (PMID 28320418, 2017). "Next, to study the effect of CD44 on GBM tumor cell phenotype, using siRNA methodology, CD44 expression was downregulated in U251 tumor cells with two different siRNAs." (PMID 28279210, 2017). "Through binding of CD44, HA can activate cytoskeleton and matrix metalloproteinases (MMPs) signaling involved in tumor progression." (PMID 28326306, 2017). "The magnetic field applied near the tumor site improved the particle accumulation on the cell surface, and the CS helped with CD44-based cellular uptake, thus improving the therapeutic activity of miR-128 in the tumor." (PMID 28587119, 2017). "On our study, on univariate analysis, CD44 staining had a significant correlation with positive lymph nodal disease, high tumor grade, and perineural/microvascular invasion." (PMID 28421110, 2017). "We reported that hyaluronic acid (HA)-coated chitosan NPs promoted the drug delivery of 5-fluorouracil (5-Fu) into tumor cells that highly expressed CD44." (PMID 28068992, 2017). "To test the in vivo relevance of CD44 overexpression in the metastatic process, we performed immunohistochemical stainings of CD44 in subcutaneous tumor xenografts as compared to lung metastases induced by OS cell tail vein injection." (PMID 29371972, 2017). "A mesenchymal, migratory CD44+/CD24- CSC subpopulation exists at the tumor edge, while an epithelial, proliferative ALDH+ CSC subpopulation resides within the tumor core." (PMID 29348905, 2017). "Whole-genome CNA analysis in FACS-sorted CD44+/CD24− and CD44−/CD24+ cells from three human NSCLC tumors and a tumor-derived cell line showed that the CD44+/CD24− cells possessed a higher content of DNA joint points and the distinctive saw-tooth profile." (PMID 28092266, 2017). "Stemness was determined by tumour sphere formation in both soft agar and liquid cultures as well as by the expression of CD44/CD24/ALDH markers." (PMID 28341962, 2017). "Yu and Stamenkovic identified a functional relationship between the hyaluronan receptor CD44, MMP9, and transforming growth factor-beta in the control of tumor-associated tissue remodeling." (PMID 28191466, 2017). "CD44 is an adhesion molecule that binds to osteopontin and hyaluronic acid, and CD44+ cells in a tumor express high levels of nuclear Bim-1, which identifies CSCs." (PMID 28942499, 2017). "These newly-discovered HA/CD44-mediated oncogenic signaling pathways delineate unique tumor dynamics with implications for defining the drivers of HNSCC progression processes." (PMID 28837080, 2017). "CD44 is a multifunctional cell membrane receptor involved in cell adhesion, tumor invasion and metastasis." (PMID 29029419, 2017). "The ability of a single cell to move from the primary tumor to metastatic site is facilitated through the transition from an epithelial phenotype (CD44+/CD24+) to a mesenchymal phenotype (CD44+/CD24-)." (PMID 28609459, 2017). "That CD44/HA binding mediates several tumor cell-specific activities and progression indicates that CD44/HA interactions play a pivotal role in cancer development." (PMID 28403901, 2017). "We also biologically validated CD44 - one of the signature genes - in GBM tumor cells and brain tissue samples." (PMID 28279210, 2017). "CSCs defined by high CD44 expression (CD44H) have been identified in various tumor types, including SCCs26–29." (PMID 29170450, 2017). "Both expression levels of CD44 and CD44v6 were higher in invasive bladder tumours than in pre-invasive tumours and normal urothelium." (PMID 29207682, 2017).